RAC1 (Rac family small GTPase 1)
Diseases named in the same sentence as RAC1 in open-access papers (continued):
Sharing a sentence is not in itself a finding about the gene and the disease.
chronic kidney disease (6 papers, 2013 to 2025). Impairment of the renal function secondary to chronic kidney damage persisting for three or more months. "A variety of chronic kidney disease models exhibit overactive Rac1, and Rac1 inhibitors protect kidneys." (PMID 39945225, 2025). "Rac1 is readily detected in the CDs of healthy controls, and its expression is preserved in CDs from patients with chronic kidney disease who maintain their typical cuboidal to columnar morphology." (PMID 38324689, 2024). "We now show that decreased Rac1 expression correlates with CD tubule damage and morphology in human individuals with chronic kidney disease." (PMID 38324689, 2024). "To further investigate the mechanism underlying the protective role of Rac-1 and ROCK inhibition in chronic renal failure we performed cell culture experiments in murine podocytes." (PMID 24244677, 2013). "By contrast, the levels of Rac1 are markedly decreased in the dysmorphic CDs of individuals with chronic kidney disease, suggesting that Rac1 expression plays a role in the preservation of CD morphology in chronic kidney disease." (PMID 38324689, 2024). "Thus, we analyzed the protein level of total Rac1 in the CDs of kidney biopsies from healthy controls or individuals with chronic kidney disease with fibrosis." (PMID 38324689, 2024). "Nevertheless, another nonsteroidal MRB, finerenone has been shown to be effective in attenuating diastolic dysfunction in chronic kidney diseases mice, transgenic mice with cardiac-specific overexpression of Rac1, and deoxycorticosterone acetate-/salt-challenged rats." (PMID 33669786, 2021). "The finding that total Rac1 levels correlate with preserved morphology in human chronic kidney disease (CKD) suggested that this is a critical event in mediating irreversible chronic injury of CDs." (PMID 38324689, 2024). "Based on some reports, Rac-1 and RhoA, as two key members of Rho GTPases, are listed as two mediators of podocyte dysfunction and therefore, their inhibition might be beneficial for handling chronic kidney diseases (CKDs)." (PMID 34861820, 2021). "In the present study we determined the impact of Rac-1 and ROCK inhibition on the progression of chronic renal failure in mice and on stretch-induced phenotype switch in cultured murine podocytes." (PMID 24244677, 2013). "We previously reported that Rac1, a Rho family small GTP-binding protein, was overactivated in several chronic kidney disease models, and that Rac1 inhibitors ameliorated renal injury, in part via inhibition of inflammation, but the detailed mechanisms have not been clarified." (PMID 26939003, 2016).
chronic lymphocytic leukemia (6 papers, 2018 to 2025). "Recently, it has been demonstrated that targeting Tiam1/Rac1 by using Tiam1 siRNA or inhibitors can reduce the chemoresistance in the proliferative and resistant pool of chronic lymphocytic leukemia (CLL) cells, which is considered to be associated with their recurrent relapses." (PMID 29416753, 2018). "In chronic lymphocytic leukemia, Rac1 and its guanine nucleotide exchange factor T-cell lymphoma invasion and metastasis 1 are important for proliferation and chemoresistance to fludarabine, a DNA intercalating purine analog." (PMID 39941828, 2025). "ROR1 expressed in chronic lymphocytic leukemia (CLL) can also serve as a receptor for Wnt5a, which induces ROR1 to associate with DOCK2 (dedicator of cytokinesis 2) and induces activation of Rac1/2." (PMID 35625853, 2022).
colitis (6 papers, 2015 to 2023). Inflammation of the colon. "Muise AM showed that carriage of the risk allele of rs10951982 results in increased Rac1 expression, and increased expression of Rac1 was associated with susceptibility to colitis." (PMID 36686718, 2022). "In dextran sulphate sodium (DSS) experimental mouse model of colitis, systemic delivery of ELMO1- lentiviral vectors attenuated colonic inflammation and promoted recovery from colonic injury via Rac1 activation." (PMID 32178475, 2020). "In this context, Rutin-rich asparagus and black beans attenuate DSS-induced colitis by modulating the colonic microbiota, resulting in improved barrier integrity and upregulation of effectors of injury repair, including Rac1." (PMID 32178475, 2020). "Lysophosphatidic acid (LPA) also promotes mucosal repair in DSS experimental mouse model of colitis, through the activation of Gαq/PLCβ1 -induced cell proliferation, and PLCβ2/Rac1 -induced cell migration." (PMID 32178475, 2020). "Rac1 activity appears to be critical for tissue repair after resolution of colitis." (PMID 32178475, 2020). "CBCs of Iqgap2-/- mice, IQGAP2 protein expression pattern observed in human colitis biopsy specimens and data on the conditional deletion of Rac1 in mouse neutrophils and macrophages suggest that the neutrophil/macrophage axis may be the predominant one in IQGAP2’s pro-inflammatory function." (PMID 26047140, 2015). "It is known that disruption of Rac1 in macrophage and neutrophils of mice protected them against dextran sulphate sodium (DSS)-induced colitis." (PMID 31249629, 2019). "The same study also showed that a conditional deletion of Rac1 in mouse neutrophils and macrophages resulted in these mice being protected from DSS-induced colitis." (PMID 26047140, 2015). "Moreover, mice with a Rac1 conditional deletion in neutrophils and macrophages are resistant to DSS-colitis, showing reduced neutrophil migration and reduced levels of IL1β and KC." (PMID 29566748, 2018).
COVID-19 (6 papers, 2021 to 2024). A disease caused by infection with severe acute respiratory syndrome coronavirus 2. "KRAS and RAC1 encode for GTPase and are respectively downregulated and upregulated in AD+COVID-19." (PMID 34948400, 2021). "While RAC1 and RAC2 share a redundant role at later stages of T-cell development, RAC1 is downregulated in COVID-19 patients with mild symptoms compared to healthy subjects." (PMID 37063865, 2023). "All three Rho GTPases, RHOA, CDC42, and RAC1, showed a significant decrease in gene expression upon age in COVID-19 patients (p-trend decreasing = 0.002, p-trend decreasing = 0.008, p-trend decreasing = 0.004, respectively)." (PMID 34696514, 2021). "Only two genes (RAC1, CXCL9) were upregulated in COVID-19(+) PU compared to the other two disease groups." (PMID 37026002, 2023). "Thus, the parallel overexpression of RAC1 and PTPN11 in AD patients with COVID-19 could be important for the enhancing of neurotoxicity." (PMID 34948400, 2021). "Four DEPs (RAC1, CAMK2G, DAAM1, and RAC2) were enriched in the noncanonical Wnt pathway and two DEPs (TLE3 and CACYBP) were enriched in the canonical pathway in the COVID-19 comparison group." (PMID 39301288, 2024).
fibrosarcoma (6 papers, 2013 to 2020). A malignant mesenchymal fibroblastic neoplasm affecting the soft tissue and bone. "Taking an siRNA approach we found that RAC1 knockdown in HT-1080 human fibrosarcoma cells that express N92I oncogenic RAC1 sensitises them to ER-stress." (PMID 29329780, 2018). "In conclusion, Rac1 activation attenuates mitogenic signalling through DYRK1B and p27 Ser10 phosphorylation, whereas it stimulates migration in 10nM-stimulated fibroblasts and fibrosarcoma cells." (PMID 25476896, 2014).
inflammatory bowel disease (6 papers, 2016 to 2022). A spectrum of small and large bowel inflammatory diseases of unknown etiology. "By contrast, the anti-inflammatory effect of sub-cytotoxic doses of 6-TG for treating inflammatory bowel disease (IBD) is thought to be primarily due to inhibition of the small GTPase Rac1." (PMID 36121863, 2022). "These drugs have also been used in the treatment of inflammatory bowel disease, which evidenced their mechanism of suppressing the small GTPase Rac1, yielding anti-inflammatory and immunosuppressive effects." (PMID 36292060, 2022). "Interestingly, thiopurines, drugs often used in the treatment of inflammatory bowel disease (IBD), have been shown to prevent activation of Rac1, resulting in a relative shift in the Rac1/RhoA balance towards RhoA." (PMID 33973626, 2021).
ischemic stroke (6 papers, 2019 to 2024). A stroke disorder caused by obstruction of blood flow to the brain, due to thrombotic (local blood clot formation) or embolic (due to a blood clot or other material traveling from another site) event. "Activation of the Ras-related C3 botulinum toxin substrate 1 (Rac1) signaling contributes to functional recovery in mice after ischemic stroke." (PMID 38543171, 2024). "The data revealed that modulation of Sig-1R/Rac1 signaling pathway-mediated phagocytic activity may be a potent therapeutic approach for ischemic stroke." (PMID 36632219, 2023). "In this study, Rac1 expression was enhanced in the NMT group compared to the MCAO model group, highlighting this DEP as a potential target for ischemic stroke treatment." (PMID 31223330, 2019).
metastatic melanoma (6 papers, 2019 to 2025). A melanoma that has spread from its primary site to another anatomic site. "For instance, in our current study, Rac1 P29S mutation was identified in the metastatic melanoma of patient 3, which would carry a potential risk for resistance to Raf-therapy." (PMID 31684113, 2019). "It destabilizes the mRNA of Rac Family Small GTPase 1 (RAC1), a known pro-tumorigenic factor highly expressed in metastatic melanoma patients, associating with its RBP Fragile X Messenger Ribonucleoprotein 1, and resulting in RAC1 destabilization." (PMID 39201617, 2024).
nasopharyngeal carcinoma (6 papers, 2018 to 2024). A carcinoma arising from the nasopharyngeal epithelium. "In addition, the up-regulation of Rac1 mRNA and Rac1 protein expression can cause methuosis in human nasopharyngeal carcinoma cells." (PMID 33542897, 2020). "The same result was created by suppression of PIKFYVE (a class III phosphoinositide (PI) kinase) and an increase in Rac1 mRNA and Rac1 protein expression in human nasopharyngeal carcinoma cells." (PMID 39768186, 2024). "RP-4, a new type of radiosensitizer derived from rhein, activates the sensitivity of nasopharyngeal carcinoma (NPC) cells to radiotherapy by targeting the Rac1-NADPH pathway." (PMID 34079763, 2021).
nephrotic syndrome (6 papers, 2018 to 2022). A collection of symptoms that include severe edema, proteinuria, and hypoalbuminemia; it is indicative of renal dysfunction. "When it comes to Rac1-associated renal disease, a type of human congenital nephrotic syndrome and treatment-resistant nephrotic syndrome have been identified that were caused by mutations in Rho GDIα." (PMID 33803946, 2021). "As Rac1, Cdc42, and RhoA are implicated in the pathogenesis of nephrotic syndrome in mice and humans, we examined whether these Rho GTPases interact with PLCE1 in cultured podocytes." (PMID 32238860, 2020). "Glucocorticoid therapy has been used to treat nephrotic syndrome for decades, and a recent study using live-cell imaging finally revealed that steroids act directly on the podocyte to reduce Rac1 activity." (PMID 31040292, 2019). "Likewise, ARHGDIA mutations in patients with steroid-resistant nephrotic syndrome increase active GTP-bound Rac1 and Cdc42 again resulting in increased podocyte motility reversed with Rac1 inhibitors." (PMID 29713631, 2018). "Likewise, the dysregulation of pathways including glomerulonephritis and Genes controlling nephrogenesis (ITGB1), Nephrin/Neph1 signaling in the kidney podocyte (RAC1), and Nephrotic syndrome (MYH9) were also determined in this study due to the cytotoxicity effect of MWCNT." (PMID 35176998, 2022). "It was shown that mutations in ARHGDIA (R120X, G173V) from individuals with treatment-resistant nephrotic syndrome were accompanied by active Rac1, but not RhoA." (PMID 33803946, 2021).
oral squamous cell carcinoma (6 papers, 2012 to 2025). "In summary, resveratrol could regulate the tumor vascular microenvironment to suppress the oral squamous cell carcinoma malignant process through the activation of ZNF750/RAC1 signaling pathway." (PMID 34176441, 2021). "The ability of resveratrol to suppress the progression of oral squamous cell carcinoma may involve activation of the ZNF750/RAC1 signaling pathway and modification of the tumor vascular microenvironment." (PMID 34176441, 2021). "This study examined whether activation of zinc finger protein 750/Ras-related C3 botulinum toxin substrate 1 (ZNF750/RAC1) signaling pathway may be involved in the ability of resveratrol to inhibit malignant progression of CAL-27 oral squamous cell carcinoma cells." (PMID 34176441, 2021). "To confirm the molecular mechanism of resveratrol in suppressing the malignant progression of oral squamous cell carcinoma cells, we further determined the expression levels of ZNF750 and RAC1 in CAL-27 cells after treatment with different concentrations of resveratrol." (PMID 34176441, 2021).
psoriasis (6 papers, 2020 to 2024). An autoimmune condition characterized by red, well-delineated plaques with silvery scales that are usually on the extensor surfaces and scalp. "RAC1 was hyperactivated in psoriatic epidermis and overexpression of RAC1 in keratinocytes caused psoriasis-like skin lesions in mice." (PMID 35075118, 2022). "Based on these features, RAC1 is likely to be an important molecule in psoriasis." (PMID 35054504, 2022). "More important to the kit, downstream effectors of mTORC2 such as the epidermal Rho small GTPases (Ras-related C3 botulinum toxin substrate 1–3 (Rac1–3), particularly hyperactivation of epidermal RAC1 has been shown to promote psoriasiform inflammation that closely resembles human psoriasis." (PMID 37371141, 2023).
rhabdomyosarcoma (6 papers, 2018 to 2022). A rare aggressive malignant mesenchymal neoplasm arising from skeletal muscle. "Because the activation of Rac1 GTPase increases myoblast fusion, Rac1 is necessary and sufficient for rhabdomyosarcoma cell migration and invasion, and syndecan-4 regulates Rac1 level, we next analyzed the role of Rac1 in syndecan-4-dependent myoblast differentiation and fusion." (PMID 35128576, 2022). "It has been reported that, in the metastasis of the rhabdomyosarcoma (RMS) cell line, guanine nucleotide exchange factor T(GEFT) accelerates the tumorigenicity by activating Rac1/Cdc42-PAK signaling." (PMID 36291059, 2022). "GEFT is highly expressed in rhabdomyosarcoma (RMS), which accelerates the tumorigenicity and metastasis of RMS by activating Rac1/Cdc42 signaling, but the regulatory mechanisms of autophagy and apoptosis are unclear." (PMID 34221974, 2021).
rheumatoid arthritis (6 papers, 2010 to 2025). A chronic, systemic autoimmune disorder characterized by inflammation in the synovial membranes and articular surfaces. "PAK1, a potential mediator of Rac1/Cdc42 signaling pathway, is involved in regulating the migration, invasion, proliferation, and inflammation of fibroblast-like synoviocytes from rheumatoid arthritis patients." (PMID 33482886, 2021). "Interestingly, prevention of Rac1 prenylation in macrophages by deleting GTPase 1, the prenylase responsible for Rac1 modification, leads to significant inflammatory response in macrophages and to rheumatoid arthritis." (PMID 34422919, 2021). "Together, this suggests that targeting Rac1 could be of clinical relevance in autoimmune disorders, such as rheumatoid arthritis." (PMID 27442895, 2017). "Given the prominent role of Rac1 in cancer, it is not surprising that Rac1 contributes to the proliferative and invasive properties of fibroblast-like synoviocytes isolated from rheumatoid arthritis patients." (PMID 27442895, 2017).
sarcoidosis (6 papers, 2020 to 2025). Sarcoidosis is a multisystemic disorder of unknown cause characterized by the formation of immune granulomas in involved organs. "Rac1 (Ras-related C3 botulinum toxin substrate 1) has also been linked to the pathogenesis of sarcoidosis." (PMID 39904950, 2025). "Deregulation of Rac1-related pathways including mTOR appears to be a relevant predisposing factor for familial sarcoidosis." (PMID 34440765, 2021). "As discussed in a previous work, the Rac1-mTOR-autophagy axis appears to be a critical pathway involved in genetic predisposition to sarcoidosis." (PMID 34440765, 2021). "Our previous data on a subset of five sarcoidosis families suggested that genetic defects in Rac1, mTOR, and autophagy-related pathways are relevant factors in familial predisposition to sarcoidosis." (PMID 34440765, 2021). "While this familial analysis confirms the genetic heterogeneity commonly reported in sarcoidosis, it allowed to stratify heritable pathogenic variants in mTOR and Rac1 signalling pathways, as well as in autophagy and vesicular transport processes." (PMID 32823753, 2020). "In addition to the implication of dysregulated Rac1-related pathways, genetic variants of some Rab proteins, such as Rab23, correlate with some phenotypes of sarcoidosis." (PMID 34440765, 2021). "Despite the difference in the two gene set sizes (329—F-SARC and 5341—CONTROL), we estimate that our previous data linking the predisposition to inherited sarcoidosis to Rac1- and mTOR-related molecular hubs was confirmed in the 13 families analyzed in the present study." (PMID 34440765, 2021). "The function of the rac1 pathway in sarcoidosis pathogenesis requires further research and experimental validation." (PMID 39904950, 2025). "Rac1 is one of the main targets of the immunosuppressive compound azathioprine (AZT) used in corticosteroid resistant forms of sarcoidosis." (PMID 32823753, 2020). "As for Rac1 mediators, we can hypothesize that genetic variations observed in IL17 receptors and/or in IL12B, encoding the common p40 subunit of IL12 and IL23, could disturb the expression of IL17 and be a predisposing state for sarcoidosis." (PMID 32823753, 2020). "Besides mTOR, JAK/STAT and Rac1 pathway, NLRP3 pathway is another important pathway activated in granuloma formation of sarcoidosis." (PMID 39904950, 2025).
Stroke (6 papers, 2010 to 2021). Sudden impairment of blood flow to a part of the brain due to occlusion or rupture of an artery to the brain. "More specifically, Rac1 inhibition with the specific inhibitor NSC23766 reduces axonal density and impairs functional recovery in animal models of stroke, whereas Rac1 overexpression promotes axonal regeneration and functional recovery." (PMID 34041508, 2021). "Deactivation of Nogo-66 receptor inhibited Rho-A, thus promoting neuronal growth, while NogoA neutralization inhibited Rho-A and activated Rac1 and Rho-B, thus enhancing post-stroke corticospinal tract plasticity." (PMID 27547178, 2016). "Based on existing evidence that Rac1 improves stroke symptoms through Pak1 signaling, the role of Pak1 in autophagy initiation might be through Axl." (PMID 34074054, 2021). "Moreover, findings indicate that Axl mediates the activation of the small GTPase Rac1, which improves post-stroke recovery and angiogenesis mediated by Pak1." (PMID 34074054, 2021). "Following neutralizing NogoA antibody delivery, massive overactivation of the small Rho GTPases Rac1 and RhoB was noticed when the antibody was administered prior to stroke, the former of which overactivated the stress kinases p38 and Jun kinase-1/2 (JNK-1/2) thus activating cell death pathways." (PMID 27547178, 2016). "Studies that target Rac1 GTPase for inhibition may thus have efficacy in preservation of neuronal survival and cognitive function following stroke in humans, and therefore should be further explored." (PMID 20830300, 2010).